TLX1 (T cell leukemia homeobox 1)
Description:
Controls the genesis of the spleen. Binds to the DNA sequence 5'-GGCGGTAAGTGG-3'.
Synonyms: HOX11; TCL3
Tractability: PROTAC: ubiquitination databases record sites on it.
Gene: Protein-coding gene on chromosome 10 (101,131,300 to 101,137,789, forward strand). Ensembl gene ENSG00000107807.
Subcellular location: Nucleus
Gene Ontology:
Molecular function: protein binding; DNA-binding transcription factor activity, RNA polymerase II-specific; DNA binding; DNA-binding transcription activator activity, RNA polymerase II-specific; DNA-binding transcription factor activity; RNA polymerase II cis-regulatory region sequence-specific DNA binding
Biological process: animal organ development; regulation of transcription by RNA polymerase II; positive regulation of transcription by RNA polymerase II; regulation of DNA-templated transcription
Cellular component: chromatin; nucleus
Genetic constraint (gnomAD): Loss-of-function variants: 6 observed, 23.51 expected, observed/expected ratio (o/e) 0.26, 90% interval 0.14 to 0.5. The upper end of that interval is the gene's LOEUF score, 0.5, which puts it in group 2 of 6, group 1 being the genes least tolerant of losing a copy. Missense variants: 418 observed, 381.74 expected, observed/expected ratio (o/e) 1.1, 90% interval 1.01 to 1.19. Synonymous variants: 217 observed, 182.19 expected, observed/expected ratio (o/e) 1.19, 90% interval 1.07 to 1.33.
Homologues: Orthologues: chimpanzee TLX1 (99% identical), rat Tlx1 (98% identical), mouse Tlx1 (97% identical), rabbit TLX1 (96% identical), macaque TLX1 (96% identical), pig TLX1 (96% identical), dog TLX1 (95% identical), guinea pig TLX1 (93% identical), tropical clawed frog tlx1 (69% identical), zebrafish tlx1 (60% identical). Paralogues in human: TLX3 (56% identical), TLX2 (53% identical), HOXA2 (20% identical), HOXB2 (20% identical), HOXB3 (20% identical), HOXD3 (19% identical), HOXD1 (18% identical), HOXB1 (18% identical), HOXA3 (18% identical), GSX2 (16% identical), HOXA1 (16% identical), HOXB4 (16% identical), and 30 more.